ALDH8A1 (aldehyde dehydrogenase 8 family member A1)
Description:
Catalyzes the NAD-dependent oxidation of 2-aminomuconic semialdehyde of the kynurenine metabolic pathway in L-tryptophan degradation.
Synonyms: ALDH12; DJ352A20.2
Tractability: Small molecule: it belongs to a druggable protein family.
Gene: Protein-coding gene on chromosome 6 (134,917,298 to 134,950,129, reverse strand). Ensembl gene ENSG00000118514.
Subcellular location: Cytoplasm
Subcellular location (Human Protein Atlas): Centrosome; Nucleoplasm
Pathways (Reactome):
Signal Transduction: RA biosynthesis pathway
Gene Ontology:
Molecular function: aminomuconate-semialdehyde dehydrogenase activity; retinal dehydrogenase (NAD+) activity; oxidoreductase activity
Biological process: retinal metabolic process; retinoic acid metabolic process
Cellular component: extracellular exosome; cytosol; cytoplasm
Genetic constraint (gnomAD): Loss-of-function variants: 39 observed, 45.78 expected, observed/expected ratio (o/e) 0.85, 90% interval 0.66 to 1.11. The upper end of that interval is the gene's LOEUF score, 1.11, which puts it in group 4 of 6, group 1 being the genes least tolerant of losing a copy. Missense variants: 605 observed, 653.51 expected, observed/expected ratio (o/e) 0.93, 90% interval 0.87 to 0.99. Synonymous variants: 233 observed, 255.91 expected, observed/expected ratio (o/e) 0.91, 90% interval 0.82 to 1.01.
Homologues: Orthologues: chimpanzee ALDH8A1 (99% identical), guinea pig ALDH8A1 (90% identical), mouse Aldh8a1 (90% identical), pig ALDH8A1 (90% identical), rabbit ALDH8A1 (89% identical), rat Aldh8a1 (89% identical), dog ALDH8A1 (87% identical), tropical clawed frog aldh8a1 (77% identical), zebrafish aldh8a1 (74% identical), Caenorhabditis elegans alh-10 (51% identical). Paralogues in human: ALDH9A1 (38% identical), ALDH1A3 (38% identical), ALDH1A2 (38% identical), ALDH1A1 (37% identical), ALDH1B1 (37% identical), ALDH2 (37% identical), ALDH1L1 (37% identical), ALDH1L2 (36% identical), ALDH5A1 (32% identical), ALDH6A1 (29% identical), ALDH4A1 (27% identical), ALDH7A1 (26% identical), and 5 more.
Diseases named in the same sentence as ALDH8A1 in open-access papers:
ALDH8A1 is named in the same sentence as 8 diseases in open-access papers, as found by Europe PMC text mining. Sharing a sentence is not in itself a finding about the gene and the disease. The quoted sentences say what the papers report.
liver cancer (2 papers, 2021 to 2022). An epithelial or non-epithelial malignant neoplasm that arises from the liver. "The results showed that ALDH1A1, ALDH1L1, ALDH1L2, ALDH3A1, ALDH3A2, ALDH5A1, and ALDH8A1 gene expressions were significantly different between liver cancer and normal tissues." (PMID 34928471, 2022). "We found that three genes ACOX2, ALDH8A1, and SCP2 were not reported in-depth in liver cancer." (PMID 33414412, 2021).
Cirrhosis (1 paper, 2021). A chronic disorder of the liver in which liver tissue becomes scarred and is partially replaced by regenerative nodules and fibrotic tissue resulting in loss of liver function. "ALDH8A1 is found decreased in nonalcoholic steatohepatitis (NASH), cirrhosis, and HCC." (PMID 35036167, 2021).
tumor (2 papers, 2020 to 2021). "Here, reduced expression of ALDH8A1, ALDOB and ARG1 were also shown in tumor tissues." (PMID 35036167, 2021). "In the TCGA_LIHC cohort, 16 of 120 genes were downregulated in HCC tissue rather than in adjacent non-tumor tissue, and 9 of 16 genes, namely, ALDH8A1, C11orf96, CLYBL, EFNB3, ENG, NPC1L1, PIM3, SEC14L2, and SLC8A1, displayed a significant difference (p < 0.05)." (PMID 33352935, 2020).
infection (1 paper, 2017). The state of being infected such as from the introduction of a foreign agent such as serum, vaccine, antigenic substance or organism. "PGM2L1, ALDH8A1, and ALDHL18A1 on the other hand all displayed a delayed response and were only significantly upregulated by 16 h of infection, while ENO3 exhibited a downregulated response at 16 h." (PMID 28993767, 2017). "In particular, only a few glycolytic/glucanogenic genes exhibited an infection-induced change in expression (PGM2L1, LDHAL6B, ENO3, ALDH8A1, and ALDH18A1)." (PMID 28993767, 2017).
ALDH8A1 also shares sentences with these, for which no sentence is quoted: breast carcinoma (1 paper); cancer (1); glioma (1); lung carcinoma (1).